FKBP5 (FKBP prolyl isomerase 5)
Diseases named in the same sentence as FKBP5 in open-access papers (continued):
Sharing a sentence is not in itself a finding about the gene and the disease.
Anxiety (continued). "Overall, these data confirm that Fkbp5 deletion in the ovBNST has a specific effect on stress-induced anxiety and highlight an anxiogenic phenotype for Fkbp5-KO." (PMID 34872938, 2021). "Of interest for our study, polymorphism in DTWD2 has shown to interact with FKBP5 in trans and GABBR1 has been associated with DNA methylation changes in newborns following maternal anxiety during pregnancy." (PMID 31040859, 2019). "In this study, we examined the association between changes in DNA methylation in two regions of FKBP5 and therapy outcome at posttreatment and follow‐up in a sample of adults (n = 111) with fear‐related anxiety diagnoses receiving exposure‐based CBT." (PMID 30334356, 2019). "Two months after ELS, we observed that ELS increased anxiety levels, specifically in mice overexpressing FKBP5, an effect that was more pronounced in females." (PMID 31167373, 2019). "Most interestingly, we also found a significant moderation effect of Fkbp5’s CG-methylation level on anxiety-like behavior in adulthood." (PMID 30655507, 2019). "More recently, a study showed that induction of FKBP5 in the basolateral (BLA) and central (CeA) nuclei of the amygdala caused an anxiety-like behavior in male mice supporting its role in modulating susceptibility to anxiety disorders." (PMID 31167373, 2019). "The higher Fkbp5’s methylation level, the longer the animals spent in the light indicating a lower level of anxiety-like behavior." (PMID 30655507, 2019). "Taken together, our results have a significant impact on our understanding mechanisms underlying the gene x environment interaction showing that anxiety and AKT signaling in the hippocampus were affected by the combination of ELS and FKBP5." (PMID 31167373, 2019). "A new specific antagonist of FKBP5—SAFIT2—reduced anxiety-like behavior even when administered peripherally." (PMID 30655507, 2019). "We generated a novel transgenic mouse to selectively overexpress FKBP5, which encodes the FKBP51 protein, in the corticolimbic system, which had no overt effects on gross body weight, motor ability, or general anxiety." (PMID 30963102, 2019). "We found that serum IGF-I levels impact on anxiety responses and modulates brain expression of FKBP5 in mice, whereas in humans, lower levels of circulating IGF-I significantly correlated with higher occurrence of stressful events and lower FKBP5 expression." (PMID 30068974, 2018). "Psychiatric disorders, including anxiety and posttraumatic stress disorder, implicate Fkbp5 as a critical gene." (PMID 29844474, 2018). "The longitudinal impact of FKBP5 deletion on anxiety was assessed in mice aged 11–14 months and then again in the same mice aged 18–22 months using the elevated plus maze (EPM)." (PMID 21935478, 2011). "Similarly, a prior study demonstrated that the attenuated induction of Fkbp5 expression reduced anxiety behavior." (PMID 35705957, 2022). "Finally, we delineate the effects of Fkbp5 manipulation in the ovBNST on anxiety-like behavior and neuroendocrinology." (PMID 34872938, 2021). "Furthermore, miR-16-5p was predicted to target to BDNF, NPY4R, GLUD1, and FKBP5, which are reported to be involved in the pathophysiology of anxiety and depression." (PMID 33737514, 2021). "Interestingly, in our study FKBP5 bin 2 methylation correlated with symptom severity, especially anxiety, as well as inversely with empathic perspective taking." (PMID 33705478, 2021). "Thus, a more precise KO of Fkbp5 in the ovBNST demonstrated an anxiogenic phenotype specific to the exploration of the unprotected arms of the EPM, aligning with the previous anxiety phenotype of Fkbp5-KO in the ovBNST." (PMID 34872938, 2021). "Our findings suggest that here stress induction of Fkbp5 may have a protective role, leading to decreased anxiety and suppression of future stress-induced HPA axis activation." (PMID 34872938, 2021).
Anxiety (continued). "Our findings suggest that stress induction of Fkbp5 in the ovBNST may have a protective role, leading to decreased anxiety and suppression of a future stress-induced HPA axis activation." (PMID 34872938, 2021). "Here, a positive correlation was found between FKBP5 methylation (bin 2) and anxiety symptoms." (PMID 33705478, 2021). "Remarkably, our results indicate that stress-induced increase of Fkbp5 in that region might have a protective role regarding anxiety-like behavior." (PMID 34872938, 2021). "Together, our findings provide a first insight into the previously unknown relationship and effects of Fkbp5 and the ovBNST on anxiety-like behavior and HPA axis functioning." (PMID 34872938, 2021). "We observed that anxiety levels were increased by the combination of FKBP5 and ELS." (PMID 31167373, 2019). "With regards to how the changes in Fkbp5 link to the changes in anxiety, it is unclear whether the increased Fkbp5 drives the altered anxiety, or whether the altered anxiety drives changes in Fkbp5 expression." (PMID 29844474, 2018). "Indeed, in wildtype mice behavioral correlates of anxiety decreased with age, whereas they appeared to increase in FKBP5−/− mice." (PMID 21935478, 2011). "In summary, ELS leads to a dysfunctional HPA feedback loop driven by FKBP5 cortisol dysregulation (high FKBP5 and low GR), which may play a mediating or exacerbating role in the anxiety, irritability, and stress-management dysregulation seen in individuals with ASD." (PMID 41514907, 2025). "In humans, common single nucleotide polymorphisms (SNPs) in FKBP5 have been identified interacting synergistically with environmental factors to increase susceptibility to develop stress-related disorders, such as post-traumatic stress disorder (PTSD), depression, and anxiety." (PMID 37726498, 2024). "Furthermore, we searched for the association of FKBP5 with subcohorts of non-demented subjects evaluated for anxiety and resting-state quantitative EEG characteristics, associated with cognitive, emotional, and functional brain activities." (PMID 35205209, 2022). "Furthermore, manipulation of Fkbp5 in the BNST has an effect on anxiety-like behaviors." (PMID 34872938, 2021). "Thus, the ovBNST seems to play a special role in the extended amygdala network and Fkbp5 in this region may act to reduce stress-induced anxiety." (PMID 34872938, 2021). "Recent work suggests that the efficacy of an FKBP5 inhibitor, SAFit2, on mediation of anxiety-like behaviors in rats withdrawing from cocaine exposure, is dependent on the specific stage of the rodent estrous cycle, further implicating the role of gonadal hormones in FKBP5 signaling." (PMID 33997155, 2021). "However, the role of Fkbp5 in the ovBNST and its impact on anxiety-like behavior have remained unknown." (PMID 34872938, 2021). "Notably, our data suggests that a stress-induced increase of Fkbp5 in the ovBNST may in fact have a protective role, leading to a transient decrease in anxiety and suppression of a future stress-induced hypothalamic-pituitary-adrenal (HPA) axis activation." (PMID 34872938, 2021). "In addition to elevated FKBP5 levels, other factors, such as hormones and activity of steroid receptors, may also impact anxiety levels in females." (PMID 31167373, 2019). "Similarly, the pGSK-3βSer9/GSK-3β ratio remained unchanged in the AMYG suggesting that the interaction of FKBP5 and stress was not implicated in the increased anxiety in rTgFKBP5-ELS mice." (PMID 31167373, 2019). "This study examined whether single nucleotide polymorphisms (SNPs) on FKBP5 gene moderate the association of positive and negative recent life events (LEs) with depressive symptoms, state-anxiety, neuroticism, and social anxiety traits." (PMID 29466454, 2018). "Here, we provide a characterization of the role of Fkbp5 in the ovBNST on HPA axis function and anxiety-related behavior." (PMID 34872938, 2021).
Anxiety (continued). "In summary, we present the first characterization of Fkbp5’s role in the ovBNST on HPA axis function and anxiety-related behavior." (PMID 34872938, 2021). "Together, this result suggests that altered FKBP5 levels can combine with ELS to uniquely alter molecular pathways and increase anxiety-like behavior in vivo." (PMID 31167373, 2019). "Individuals with higher FKBP5 methylation in utero thus may have an over-active cortisol response pathway at the time of birth, and may be predisposed to develop disorders related to elevated HPA axis activity, such as post-traumatic stress disorder or anxiety." (PMID 25115650, 2014). "The behavioral correlates of anxiety in the EPM were significantly affected by age, and this change depended on the genotype at FKBP5 as reflected by a significant age*genotype interaction." (PMID 21935478, 2011). "Previous studies show that global FKBP5 knockout does not affect anxiety behavior neither in basal or stressed conditions." (PMID 39438757, 2025). "Increased FKBP5 expression suggests decreased GR sensitivity to ligands and the possible inhibition or reduction of the glucocorticoid response element (GRE)-dependent transcription of genes in brain regions responsible for stress and fear/anxiety modulation." (PMID 39595978, 2024). "Additionally, mice treated with a recent FKBP5 inhibitor during CSD show reduced social withdrawal and anxiety-like behavior, which is in line with our data." (PMID 37149657, 2023). "In the EPM test, we found that Fkbp5-KO but not WT mice exhibited anxiety-like behavior with less time spent in the open arm after LPS injection." (PMID 35705957, 2022). "DNA methylation of the promoter region of the FKBP5 gene was not a significant predictor of anxiety symptoms." (PMID 35185646, 2022). "Work in healthy human subjects has also demonstrated a sex-specific effect, with mRNA levels of FKBP5 collected from blood correlating with scores on depression and anxiety rating scales in women, but not in men." (PMID 33997155, 2021). "We hypothesized that exposure to maternal pregnancy-related anxiety in utero may program child gender-specific neurobehavior via gender-specific DNA methylation of HSD11B2, NR3C1 and FKBP5 genes in placenta." (PMID 34715840, 2021). "Manipulations of Fkbp5 in other regions, such as the dorsal hippocampus of mice, did not alter anxiety-like behavior." (PMID 34872938, 2021). "Another previous study showed that overexpression of FKBP5 in the dorsal hippocampus did not have an effect on anxiety-like behaviors." (PMID 31167373, 2019). "These viral studies have demonstrated that FKBP5 overexpression in the amygdala, but not the hippocampus, can increase anxiety-related behavior." (PMID 30963102, 2019). "Thus, in the present work, we analyzed anxiety-like responses to TBI and/or predator exposure, and FKBP5 expression in mice with varying levels of serum IGF-I." (PMID 30068974, 2018). "Fkbp5-KO did diminish the DEX-induced anxiety-like, but not depressive-like, behavior." (PMID 35705957, 2022). "Notably, Fkbp5-KO but not wild-type (WT) mice showed anxiety-like behaviors 7 days after LPS injection (LPS-D7)." (PMID 35705957, 2022). "However, no changes were seen in ventral hippocampus and a different study found that overexpression of FKBP5 in the dorsal hippocampus did not have an effect on anxiety-like behaviors." (PMID 34205191, 2021). "This might also explain the lack of anxiety-related phenotypes in the full Fkbp5-KO mice, where Fkbp5 is neither expressed in the ovBNST nor in the amygdala." (PMID 34872938, 2021). "Gene expression studies show reduced FKBP5 expression in CKO mice; this would decrease the suppression of glucocorticoid receptor (GR) signaling thereby enhancing their feedback inhibition, consistent with their dampened corticosterone level and anxiety-like behaviors upon stress induction." (PMID 34830120, 2021).
Anxiety (continued). "Thus, no influence of Glo1 expression on anxiety-related behavior could be observed in Fkbp5-/- and Fkbp5+/+ mice." (PMID 26011321, 2015). "While a global knock-out (KO) of Fkbp5 did not affect anxiety-like behavior, reducing FKBP51 in the amygdala decreased stress-induced anxiety-like behavior." (PMID 34872938, 2021). "However, the scores of the factor characterized by FKBP5, NR3C1 and HSD11B2 did not mediate the relationship between maternal pregnancy-related anxiety and preschoolers’ emotional symptoms and hyperactivity." (PMID 34715840, 2021).
post-traumatic stress disorder (54 papers, 2011 to 2025). An anxiety disorder precipitated by an experience of intense fear or horror while exposed to a traumatic (especially life-threatening) event. "For example, elevated FKBP5 expression is associated with dendritic spine density changes in the orbitofrontal cortex of subjects with posttraumatic stress disorder (PTSD)." (PMID 33673722, 2021). "For example, Klengel and Binder24 showed how methylation of a functional glucocorticoid response element (FKBP5) in adults with a history of child abuse increased the risk for posttraumatic stress disorder after trauma exposure in adulthood." (PMID 30646399, 2018). "FKBP5 SNPs and gene expression levels are associated with the onset of posttraumatic stress disorder (PTSD) and anxiety disorder in humans." (PMID 27527158, 2016). "FK506 binding protein (FKBP5) is a negative regulator of cortisol response, FKBP5 methylation has been linked to brain morphology and mental disorder risk, and genetic variation of FKBP5 was associated with post-traumatic stress disorder in adults." (PMID 25115650, 2014). "Previous studies of FKBP5 have observed associations with post-traumatic stress disorders, and PTSD is characterized by hypervigilance and hyperarousal." (PMID 25115650, 2014). "A recent study demonstrated that the risk for post-traumatic stress disorder is associated with FKBP5 genotype-specific CT-dependent demethylation, in support of FKBP5 genotype by CT interactions in the development of stress-related disorders later in life." (PMID 24658422, 2014). "Notably, FKBP5 has been implicated in neurological disorders, including post‐traumatic stress disorder, Alzheimer's disease, Parkinson's disease, and schizophrenia." (PMID 40254776, 2025). "Importantly, FKBP5 epigenetic regulation has been shown to be linked to genetic predisposition for posttraumatic stress disorder (PTSD)." (PMID 41514907, 2025). "The epigenetic regulation of microRNA (miRNA) expression related to the FK506-binding protein 5 (FKBP5) gene may contribute to the risk of stress-related disorders such as posttraumatic stress disorder (PTSD)." (PMID 32098997, 2020). "FKBP5 is an important endogenous regulator of the stress response system, and genetic variations have been associated with many stress-related disorders, such as maladaptive emotional behavior, posttraumatic stress disorder, anxiety disorders and borderline personality disorder." (PMID 40764371, 2025). "Human individuals with post-traumatic stress disorder consistently have decreased levels of FKBP5, which dampens the cortisol response." (PMID 40420851, 2025). "Accumulating studies have demonstrated that FKBP5 SNPs are strongly related to several psychological affective diseases, including posttraumatic stress disorder (PTSD), borderline personality disorder, and suicidal tendencies." (PMID 37051166, 2023). "Methylation of the ADCYAP1R1 gene in peripheral blood DNA was found to be associated with post-traumatic stress disorder (PTSD) and methylation of FKBP5 in lymphocytes was associated with both genetic risk for PTSD and early life adversity." (PMID 24691403, 2014). "Moreover, hypomethylation in the FKBP5 gene has been found in veterans exposed to combat trauma who present post-traumatic stress disorder (PTSD)." (PMID 37190549, 2023). "It was suggested that miR-15a-5p, let-7d-5p, miR-511-5p, and miR497a-5p, which target the two key post-traumatic stress disorder-related genes, FKBP5 and BDNF, were differentially modulated in the several brain regions of the post-traumatic stress disorder-related susceptible and resilient mice." (PMID 36430957, 2022). "FKBP5 polymorphisms are also associated with altered induction of mRNA, changes to hippocampal size, as well as diseases associated with alterations in the hypothalamic-pituitary-adrenal (HPA) axis, such as post-traumatic stress disorder (PTSD)." (PMID 25115650, 2014).
post-traumatic stress disorder (continued). "In line with preclinical findings, post-mortem human brain studies also report elevated FKBP5 mRNA levels in cortical regions across different psychiatric disorders, including depression, post-traumatic stress disorder (PTSD), and schizophrenia." (PMID 38540789, 2024). "Our group and others have also reported that FKBP5 levels in the postmortem orbitofrontal cortex are inversely correlated with dendritic mushroom spine density in mixed psychiatric cases with a history of severely stressful life events and in post-traumatic stress disorder." (PMID 36729133, 2023). "Epigenetic changes have been well-established in BDNF, COMT, FKBP5, NR3C1, SLC6A4, and DRD2, genes associated with psychiatric disorders, including schizophrenia, major depressive disorder (MDD), bipolar disorder (BP), post-traumatic stress disorder (PTSD), and autism spectrum disorder (ASD)." (PMID 41234420, 2025). "The stress-related gene FKBP5 has been related to dysregulated glucocorticoid receptor (GR) signaling, showing increased GR sensitivity in trauma-exposed subjects with post-traumatic stress disorder (PTSD) but not in those without PTSD." (PMID 32170058, 2020).